TLR4 (toll like receptor 4)
Diseases named in the same sentence as TLR4 in open-access papers (continued):
Sharing a sentence is not in itself a finding about the gene and the disease.
infection (continued). "Infection by periodontal pathogens activates macrophages via Toll-like receptor 4 (TLR-4), which subsequently activates inflammatory signaling pathways, including the nuclear factor kappa B (NF-κB) pathway." (PMID 40699787, 2025). "In vitro studies revealed that ExPEC infection upregulated TLR4 expression in human brain microvascular endothelial cells and induced pyroptosis and tight junction protein degradation." (PMID 40821830, 2025). "For example, the costimulation of TLR2 and TLR4 in macrophages synergistically increases the production of proinflammatory cytokines, amplifying the overall immune response to infections." (PMID 41295183, 2025). "Results revealed 11 core genes, including TLR4, critical for immune responses against the infection, with TLR4 activating key inflammatory pathways." (PMID 40431572, 2025). "TLR4 is the prototype immune receptor and central to infection defense via detecting lipopolysaccharide (LPS)." (PMID 41383593, 2025). "For these experiments, we first established a primary A. baumannii infection by inoculating tlr4 mutant mice with 105 CFU of strain G636." (PMID 40817088, 2025). "Here we show that TcpC intensified TLR4-dependent pro-inflammatory cytokine secretion by human epithelial cells upon infection with CFT073." (PMID 41310197, 2025). "Together, these results demonstrated that TLR4 expression was upregulated during ExPEC infection, and its inhibition reduced ExPEC-induced pyroptotic cell death in brain endothelial cells." (PMID 40821830, 2025). "TLR2 and TLR4 exhibit strong co-expression, suggesting coordinated regulation during udder infection." (PMID 40453956, 2025). "Key findings include significant associations between polymorphisms in TLR4 (rs4986790), IL-10 (rs1800896), TNF-α (rs1800629), and MBL2 (rs1800450) with infection susceptibility, disease severity, and survival outcomes." (PMID 40692949, 2025). "Administration of TLR4 or TLR3 agonists or intranasal infection of mouse-adapted influenza virus (H1N1) or coronavirus (MHV-A59) induced CD69 in lung ECs." (PMID 40617350, 2025). "The selective effect of TLR4 knockout on HMPV-mediated TNF was further reflected at the protein level: secreted TNF was significantly reduced at 20 h post-infection in TLR4 KO cells, while secretion of the IFN-inducible chemokine CXCL10 remained unchanged." (PMID 41346628, 2025). "To understand the molecular mechanisms underlying TLR4 deficiency-mediated protection, we performed RNA sequencing analysis of brain tissues from WT and TLR4-/- mice after RS218 infection." (PMID 40821830, 2025). "Taken together, these features support the use of TLR4 agonists as stand-alone therapeutic agents or antimicrobial adjuvants in infection-prone populations." (PMID 41568029, 2025). "At 24h post-infection, miR-1236-3p-m and si-TLR4 significantly reduced the expression of TLR4 and downregulated the phosphorylation level of p65, as well as the expression of TRAF6 and MyD88." (PMID 40502714, 2025). "To help resolve this valid scientific concern we did a study in which we compared infection with L. interrogans in mice expressing competent tlr4 (C57BL6, C3H/HeN) versus mice that are tlr4 hyporesponsive (C3H/HeJ)." (PMID 40445994, 2025). "To determine to which degree the invasive capabilities of NTHi depend on the engagement of TLR4 with LOS, we inhibited TLR4 using pre-treatment of THP-1 cells with anti-TLR4 mouse IgG prior to infection, with mouse IgG1 serving as an isotype control." (PMID 40137696, 2025). "Survival analysis showed that while all WT mice succumbed to infection within 72h, TLR4-/- mice exhibited remarkable resistance with 100% survival throughout the 96h observation period." (PMID 40821830, 2025). "CD36, a scavenger receptor localized on the cell surface, participates in several cell functions including lipid metabolism and collaborate with TLR4 in the LPS recognition during early stages of infection." (PMID 40725160, 2025).
infection (continued). "In the spleen, a reduction in TLR-4 transcription has been detected in infected groups compared to uninfected individuals, while in the skin during the earliest stages of infection, an increase in TLR-9 transcription was revealed." (PMID 40725420, 2025). "Our results indicate that FEBF effectively downregulated TLR4, MyD88, and NF-κB p65 protein expression during the early phase of infection." (PMID 40308697, 2025). "Dual blockade strategies further attenuated infectivity: concurrent inhibition of FcγRI+TLR4 reduced infection rates to T0-equivalent levels, whereas FcγRIIa+TLR4 blockade retained residual infectivity exceeding T0." (PMID 40557164, 2025). "In vitro infection with C. sakazakii led to increased abundance of IL-1β, TLR4, the inflammasome components NLRP3 and caspase-1, and the adapter protein MyD88 in human colon HT-29 cells." (PMID 41283989, 2025). "To investigate the role of TLR4 in ExPEC infection, we first examined its expression in hCMEC/D3 cells infected with RS218." (PMID 40821830, 2025). "This differential regulation by TLR2 and TLR4 highlights the complex interplay between host receptors during infection." (PMID 40821830, 2025). "The TLR4/NF-κB pathway is a key signaling pathway in the immune system for detecting and responding to infection, inflammation, and external stimuli." (PMID 38504994, 2024). "In this study, we evaluated Ghrelin serum levels and changes in TLR4/MyD88/NF-κB pathway proteins and inflammatory factors in AE patients and E. multilocularis mouse models at different stages of infection (-4, -8, and -12 weeks)." (PMID 39749332, 2024). "As a pivotal member of the TLR family and a prototypical inflammatory mediator, TLR4 serves as an intermediary linking innate immunity to adaptive immunity and infection to inflammation." (PMID 39861077, 2024). "In the context of E. multilocularis infection, we observed that the TLR4/MyD88/NF-κB signaling pathway remains suppressed in the early stages of infection; however, it becomes activated after eight weeks." (PMID 39749332, 2024). "TLR2 and TLR4 represent some of the initial immune responses employed by the host to combat infections, serving a crucial function in identifying pathogens." (PMID 39749340, 2024). "This process is induced by various cellular activation signals, including stimulation of tumor necrosis factor receptor (TNFR) and toll-like receptor 4 (TLR4) in the course of inflammation or infection." (PMID 38764576, 2024). "In mouse macrophages, TLR4 enhanced the antiviral innate immunity in response to the tick saliva peptide HIDfsin2, thereby restricting the infection and transmission of the tick-borne SFTSV." (PMID 38786177, 2024). "During infection, IL-22BP is down-regulated in response to Toll-like receptor 315 and Toll-like receptor 4 stimuli, as well as DNA sensing by the inflammasome." (PMID 38101567, 2024). "Upon infection, LPS triggers pro-inflammatory signaling pathways activating Toll-like receptor 4 (TLR4) present in the plasma membrane of numerous immune cells, including macrophages, and some non-immune cells." (PMID 38652315, 2024). "This study's results align with previous studies showing that LPS via the TLR4 pathway in the early phase of infection can activate MyD88, which triggers IRAK signal transduction." (PMID 38049119, 2024). "During infections, heterophils are primed by IFN-γ, which promotes their binding with TLR-4, which leads to higher phagocytic activity with the advancement of infection." (PMID 39457937, 2024). "Seven days after infection, levels of TLR4 and phosphorylated p65 (p-p65; NF-κB pathway) remained unchanged among all genotypes." (PMID 38301068, 2024). "Studies have shown that TLR4 activation by LPS infection and IFN-γ, which is one of the critical cytokines controlling inflammation, can impair the self-renewal capacity of HSCs." (PMID 38267561, 2024).
infection (continued). "Our study showed that in the early stage of S. mansoni infection (two weeks post infection) Swiss mice showed higher expression of TLR4, TLR6 and Myd88 mRNA in the liver than BALB/c and C57BL/6." (PMID 38896633, 2024). "The in vivo immunofluorescent findings show consistency with RT-qPCR and immunoblot results, which indicates that PE_PGRS38 downregulates the expression of TLR4 and NF-κB in the host during infection." (PMID 38785795, 2024). "By interacting with TLR4, LPS activates macrophages to release pro-inflammatory cytokines and chemokines that recruit neutrophils from the bloodstream to the infection site." (PMID 39687793, 2024). "During pathogenic infection in the gut, innate and adaptive immune cells act together through IFN-γ and TNF-α secretion to enhance TLR4 mRNA and its protein expression by epithelial cells to induce pathogen recognition and innate immunity activation." (PMID 38473881, 2024). "S100A8/A9 plays an important role in protecting the body from pathogen infection through multiple inflammatory pathways mediated by TLR4 or RAGE." (PMID 39061526, 2024). "Compared with DDX5+/+ mice, DDX5 was expressed at a much lower level in the lungs of DDX5+/- mice, whereas the opposite was observed for TLR4 during 0–24 h post-infection with P. multocida." (PMID 38182816, 2024). "Since we did not detect the effect of the N protein, we focused on another TLR4-dependent pathway that is believed to be involved in cell infection with the SARS-CoV-2 virus." (PMID 38807115, 2024). "TLRs, especially TLR2 and TLR4, significantly affect post-infection and lipopolysaccharide-mediated regulation of gastrointestinal motility." (PMID 39749341, 2024). "To overcome the current limitations with the acellular vaccine, we incorporated a novel TLR4 agonist, BECC438b, into both IM and IN acellular formulations to determine its ability to protect against infection in a murine airway challenge model." (PMID 38323817, 2024). "Extracellular HMGB1 interacts with various binding partners such as receptor for the advanced glycation end product (RAGE), and Toll-like receptor 4 (TLR4) to trigger inflammation following infection or injury." (PMID 37507374, 2023). "For example, polypropyletherimine dendrimer glucosamine (PETIM-DG), an oral Toll Like Receptor-4 (TLR4) antagonist, can control resolution of the infection-related-inflammatory response and prevent neutrophil-mediated gut wall disruptions." (PMID 38091314, 2023). "The bacterial killing capacity of S. Typhimurium in TLR4 macrophages was dramatically higher than that in the WT group at MOI 10 after infection with live S. Typhimurium." (PMID 36876076, 2023). "An intriguing finding is that the oral taxonomic enrichment of the lung microbiome increases microbiota metabolite concentrations and decreases alveolar macrophage TLR4 responses, with the latter leading to reduced infection clearance." (PMID 37109545, 2023). "Of note, similar to TNF-α and IL-6, the quantity of IL-27 decreased when TLR-2 or TLR-4 were blocked prior to infection." (PMID 36863206, 2023). "This work also suggests such a role for IRE1 RNase in the pro-inflammatory response following infection by exogenous pathogens activating TLR4 or other pathogen recognition receptors (PRRs)." (PMID 37711626, 2023). "In fact, activation of TLR2 and TLR4 by HA has been shown to induce antimicrobial peptides and help protect vaginal tissue from infection." (PMID 37549960, 2023). "Analyses of the IL-8 responses following challenge of the TLR4 siRNA cells were more strain variable and supported minor roles for LPS, and TLR4 in the RT4 bladder cell innate response to an acute infection." (PMID 37032848, 2023). "A study performed in African American women, (TLR1) rs5743618TT was associated with CT infection and women with PID who had rs1927911 CC (TLR4) and had high chances of contracting the CT infection." (PMID 37937275, 2023).
infection (continued). "Like TLR2, the level of TLR4 was significantly increased with increasing time points post infection." (PMID 36707891, 2023). "In TLR4-deficient mice, recruitment of CD14+ and NK cells was diminished upon infection while viral clearance was delayed." (PMID 37896776, 2023). "Numerous studies have demonstrated the regulatory role of TLR4 in the activation of proinflammatory cytokines and leukocytes during infection-induced preterm labor." (PMID 37867523, 2023). "TLR4+ MDSCs have been sparsely identified in select infection scenarios, yet notable discoveries have arisen in the realm of cancer and inflammatory pathologies." (PMID 37524886, 2023). "In normal conditions, renal TLR4 expression is low, however, the expression of this molecule increases in response to renal injury and/or infection." (PMID 36674930, 2023). "Upon infection, bacteria trigger inflammatory response via the Toll-like receptor 4 (TLR4)/NF-κB signaling pathway in macrophages." (PMID 36864027, 2023). "During activation of NF-κβ signalling pathway, the repressive mark H4K20me3 is decreased, which represses expression of TLR4 in macrophages important for recognition of LPS during infection-activated immune response." (PMID 37731322, 2023). "Taking into account the host’s immune status, the TLR4 gene expression was statistically higher in the skin of host from A group than in host from AS group at the beginning of the infection." (PMID 37242301, 2023). "infection was observed as having increased expression of TLR2 and TLR4 at the beginning of infection." (PMID 37242301, 2023). "Suppression of the microRNA occurs soon after infection, resulting in the increased expression of TLR4." (PMID 37325809, 2023). "The D299G and T399I substitutions in human TLR4 have been shown to exacerbate or ameliorate inflammation in different diseases and disease models, including infection, inflammation, and cancer." (PMID 37768050, 2023). "After TLR4 recognizes LPS infection, it activates intracellular tail-like structures, recruits myeloid differentiation factor MyD88, activates NF-κB, and further releases pro-inflammatory cells." (PMID 37268931, 2023). "In a mouse model of infection, blocking the Birc3/TLR4/Myd88 signaling pathway showed a protective effect against carbapenem-resistant K. pneumoniae." (PMID 38274787, 2023). "DSP analysis showed that TLR4 cascades were activated by infection, corresponding to the histopathological inflammation." (PMID 37369668, 2023). "During infection, TLR4 itself was unchanged, but TLR4 played an important role in regulating PEDV infection and proinflammatory cytokine expression." (PMID 37242424, 2023). "While TLR4 would impair and control the infection spreading throughout the initial stage of infection, the conger immune receptor, TLR2, was reported beneficial for reducing inflammatory levels associated with the infection." (PMID 36911530, 2023). "TLR4 can regulate infection‐induced or sterile inflammation by endogenous molecules, and apoptotic process." (PMID 37773705, 2023). "As one of the important PRRs, TLR4 recognizes bacterial LPS and induces the host’s innate immune responses, promoting innate immune system resistance to infections." (PMID 37443803, 2023). "After B. abortus infection, TLR4 KO BMDMs also show a decreased upregulation of glycolysis, which is intriguing since B. abortus reduces activation of TLR4 by its LPS during infection." (PMID 36475773, 2023). "We conducted a case–control study to compare the role of TLR4/TLR9 gene polymorphisms between HR-HPV transient and persistent infections, as well as between HR-HPV single and multiple infections." (PMID 36915050, 2023). "It has been demonstrated that calprotectin expression in neutrophils is regulated via the TLR4 pathway in response to Spike protein, and that the adaptor Docking Protein 3 restrained the production of calprotectin during infection when TLR4 was engaged." (PMID 37175768, 2023).
infection (continued). "The MyD88/TRIF/NF-κB pathway, which is considered the primary regulatory downstream pathway of TLR4, mediates various inflammatory processes during LPS-induced infection." (PMID 37446388, 2023). "At 3 h post infection the TLR4 level was 180% which increased significantly at 6 h (220%, p < 0.0001), 12 h (297%, p < 0.0001) and reached to the level 312 (p < 0.01) at 24 h post infection when compared to the level expressed at 0 h post JEV infection." (PMID 36707891, 2023). "The infection with Salmonella upregulated statistically significantly TLR4 mRNA expression in all Salmonella-challenged minipigs (LT2, RP36+LT2, RP37+LT2, and LA+LT2) compared to non-challenged ones (GF, RP36, RP37, and LA)." (PMID 38003758, 2023). "Our data suggest that hypoxia increases expression of chemokine ISGs in monocytic THP-1 cells upon infection with SARS-CoV-2 by enhancing spike protein-mediated TLR4 signaling." (PMID 37377965, 2023). "Previous studies have shown how non-B cell-intrinsic mechanisms including the recruitment of discrete Sca-1+ monocyte populations, TLR4 expression and IL-12-mediated suppression of Tfh cells can impair GC formation after STm infection." (PMID 36950118, 2023). "LipL21 is one of the abundant outer membrane lipoproteins in pathogenic L. interrogans serovar Copenhageni, which is highly expressed during infection and binds to Toll-like receptor 4 (TLR4) and complement regulators for modulating the innate response." (PMID 36853003, 2023). "TLR4 is investigated in different pathologies and found to play a role in hepatic injury resulting from infection or toxins." (PMID 37649466, 2023). "Goldfish during infection by the oviparous monogenean Dactylogyrus intermedius expressed high TLR4, TLR5, TLR20 and TLR22 in gills, head kidney, liver and spleen." (PMID 37759598, 2023). "TLR4 can regulate both infection-induced or sterile inflammation by endogenous molecules, and apoptotic process." (PMID 36600293, 2023). "In another study, infection of Tlr4−/− mice with the phylogenetically related SARS-CoV resulted in significantly higher virus replication and disease severity compared to wildtype mice." (PMID 38034686, 2023). "In response to infection, the leptomeningeal vasculature of Tlr4-/- mice showed minimal changes in the distribution of CLDN5 and very few regions of Sulfo-NHS-biotin leakage." (PMID 37318981, 2023). "The vascular response to infection appears to be largely driven by TLR4 signaling, as determined by the nearly identical responses induced by infection and LPS administration and by the blunted response to infection in Tlr4-/- mice." (PMID 37318981, 2023). "Having shown that the increased intracellular burden of infection following TLR4 inhibition or knockout is a result of elevated phagocytosis and not proliferation, we next sought to identify the plasma membrane receptor responsible for this increase in uptake." (PMID 37580395, 2023). "Our results clearly show that cytokine responses of MDMs to live GBS are different from those to purified TLR2 or TLR4 agonists or heat inactivated bacteria, emphasizing the importance of using live bacteria in experimental models of infection." (PMID 38035076, 2023). "In response to infection, toll like receptor 4 (TLR4) on macrophages recognises LPSs to induce the expression of FMS related tyrosine kinase 4 (FLT4)." (PMID 38066566, 2023). "The expressions of TLR3 and TLR4 were increased by infection with different ZIKV strains, and the expression of TLR5 appeared unaffected 2 days after infection." (PMID 36834929, 2023). "Macrophages were infected for a fixed time with S. Typhimurium and then examined the elimination capacity of S. Typhimurium in TLR4 overexpressing macrophages and WT macrophages after 1 h post infection." (PMID 36876076, 2023).